IL27 (interleukin 27)
Diseases named in the same sentence as IL27 in open-access papers (continued):
Sharing a sentence is not in itself a finding about the gene and the disease.
infection (continued). "Our results suggest that IL-27 has a greater predictive value in patients with positive bloodstream infections compared with infections from other body compartments." (PMID 26514771, 2015). "Th1 cells are the major source of IL-10 during this infection, as in other chronic parasitic infections, and it is induced by IL-27." (PMID 26646149, 2015). "It has been shown in vivo that IL27 reduced inflammation by suppressing excessive Th1 immune responses during infection, and in vitro in several T cell subtypes it has been shown that IL27 induced the production of the anti-inflammatory IL10." (PMID 26663990, 2015). "The importance of IL-10 induction on T cells by IL-27 has already been shown in many disease models, such as infection with T. gondii, L. major, or Salmonella and EAE." (PMID 25633106, 2015). "More recent studies have suggested that IL-27 also has the function to inhibit immunopathology via downregulation of active CD4+ T cells during infections, particularly with intracellular protozoan parasites." (PMID 26222157, 2015). "During infection with T. gondii, L. major, or Salmonella, IL-27 is required for the generation of T-bet+CXCR3+ Treg, which produce IL-10 and limit T effector responses." (PMID 25633106, 2015). "Dampening accumulation of highly activated CD4+ T cells by IL-27 signaling has also been recently observed in infection with other microorganisms, particularly intracellular protozoan and bacterial pathogens." (PMID 26222157, 2015). "The expression of mRNA encoding several interleukins was also induced in the infected mouse uterus at 28 days post-infection, including Il1b, Il12a, Il12b, Il16, Il18, and Il27." (PMID 26779389, 2015). "The expression of the IL-27p28 subunit in the influenza virus-infected respiratory tract peaks at the later phase of infection when viral titers are at a decline, which is consistent with the suggested role of IL-27 in limiting the immune response." (PMID 24809349, 2014). "The data also suggest a therapeutic potential of IL-27, as mice treated with recombinant cytokine at later stages of infection exhibited decreased immunopathology and showed improved survival." (PMID 24809349, 2014). "In line with this concept, we observed protective effects when rIL-27 was administered in a later phase of infection, starting at the peak of viral load when also the endogenous IL-27 production is near its highest level." (PMID 24809349, 2014). "Our data thus provide important new information on how IL-27 regulates CD4+ T cell responses during infection." (PMID 23593003, 2013). "One would imagine that animal models of infection (using SIV in rhesus macaques for example) will be required to test the efficacy of IL-27 prior to Phase I clinical trials beginning." (PMID 23527130, 2013). "In this study we have defined the molecular mechanisms by which IL-27 restricts Th1 immune responses during infection." (PMID 23593003, 2013). "In summary, our study has significantly expanded our understanding of how IL-27/WSX-1 signalling regulates Th1 responses in vivo during infection." (PMID 23593003, 2013). "On the other hand, it has been shown that IL-27 also suppresses the development of Th1, Th2 and Th17 subsets in later phases of infection." (PMID 22761702, 2012). "Specifically in the context of infection with T. gondii, IL-27 has been shown to play a significant role in regulating Th1 activation and preventing immunopathology (reference 30)." (PMID 22479310, 2012). "Because EBI3 is a subunit of the heterodimeric cytokine, IL-27, we tested the ability of serum IL-27 protein concentrations to predict infection." (PMID 23107287, 2012). "At a cut-point value of ≥5 ng/ml, serum IL-27 protein concentrations predicted infection with a specificity and a positive predictive value of >90%, and the overall performance of IL-27 was generally better than that of PCT." (PMID 23107287, 2012).
infection (continued). "IL-27 is provoked by a number of intracellular pathogens and has both pro- and anti-inflammatory functions that contribute to control of infection (as reviewed,)." (PMID 22428026, 2012). "At the time of infection IL-27 promotes bacterial persistence and compromises host defense." (PMID 40977737, 2025). "Together, we were able to employ a targeted tissue approach to explore IL-27 expression based on bacterial signature visualized by whole animal imaging and identified a changing dynamic of IL-27 production in the liver during infection that warranted further analysis of those cell populations." (PMID 40682363, 2025). "Both viruses expressed IL-27 after infection of the murine and Syrian hamster cells in vitro." (PMID 40350204, 2025). "Thus, during infection, the ability of IL-27 to act on HSPC provides a regulatory brake on differentiation to limit monocyte induction and preserve HSPC stemness." (PMID 39868131, 2025). "Thus, during infection, the ability of IL-27 to act on HSPCs provides a regulatory brake on differentiation to limit monocyte induction and preserve HSPC stemness." (PMID 41396163, 2025). "IL-27 limits infection-induced hematopoietic stem and progenitor cell (HSPC) polarization." (PMID 41396163, 2025). "An alternative function of IL-27 includes modulating inflammatory responses during infection." (PMID 41036542, 2025). "IL-27 regulates monopoiesis during infection in a cell-intrinsic manner." (PMID 41396163, 2025). "The data that DCA–VPA suppresses IL27 expression in male T lymphocytes may also be important for treating infection." (PMID 38543303, 2024). "Furthermore, the Salmonella-based vaccine increased IL27, which is produced by DCs and macrophages in response to infection or inflammation." (PMID 38543910, 2024). "The EC50 value for IL27 was 2.870 ng/mL following infection at MOI 0.5." (PMID 38932287, 2024). "The regulatory functions of IL-27 include inhibition of Th2 and Th17 cell differentiation, and the induction of IL-10-producing Type 1 regulatory cells (Tr1) cells controlling immunopathology in the setting of infection." (PMID 38966644, 2024). "Collectively, IL-27 differently regulates T-cell function according to distinct infection." (PMID 38566992, 2024). "Furthermore, we identified 1959 commonly expressed DEmRNAs, including IL27, Nos2, and Cxcr2, across two infection stages." (PMID 38229193, 2024). "IL‐27 may directly modulate precursor memory CD4+ T cells as observed in the gene expression patterns during acute infection." (PMID 37855243, 2023). "From infection standpoint, IL-27 can be detrimental or protective." (PMID 37781399, 2023). "Two cytokines, IL‐27 and GM‐CSF, were decreased in amniotic fluid in response to infection." (PMID 37259639, 2023). "Furthermore, this study suggests that neutralizing both IL-27 and IL-10 better control M. tuberculosis, thus co-neutralization is of better therapeutic value during infection." (PMID 36863206, 2023). "IL-27 driven emergency granulopoiesis response is an important process to combat against infection." (PMID 37781399, 2023). "Importantly, our model demonstrated a further increase in IL-27 expression during infection in the spleen, a known site of infection exhibiting high bacterial burden." (PMID 36891292, 2023). "In contrast, IL-27 increased HIV-1 production when added to infected cells 4 days after infection." (PMID 36602368, 2023). "To understand the impact of IL-27 on regulation of the neonatal host response to infection, we profiled the transcriptional response in uninfected control and E. coli O1:K1:H7-infected neonates at 1-day post-infection." (PMID 36891292, 2023). "As shown, IL-27 reduced infection of macrophages at lower levels of infection with vaccinia virus." (PMID 37153622, 2023).
infection (continued). "Taken together, these results denote that neutralization of IL‐27 during acute infection induced and maintained cellular and humoral immune responses that are protective against recall challenge infection, although chronic infection is required for the maintenance of the protective ability." (PMID 37855243, 2023). "We found human macrophages also produce IL-27 upon infection with M. tuberculosis." (PMID 36863206, 2023). "IL-27 showed IFN-independent anti-CMV effects for 2 days after infection." (PMID 37153622, 2023). "However, if IL-27 induces IL-10 at a later time during infection, immunopathology is reduced while preserving the antiviral immune response." (PMID 35634328, 2022). "Interestingly, we found that IL-27 stimulation prior to infection led to a significant increase in Mx1 expression, which was greater than infection alone." (PMID 36678402, 2022). "Interestingly, it is understood that IL-27 has diverse T-cell-dependent functions relying on the confronting Leishmania species and the stage of the infection." (PMID 35090305, 2022). "Thus, elucidation of the functions of IL-27 in the context of infection is essential to improve our understanding of protective vs. pathogenic host immunity." (PMID 36028492, 2022). "Our analysis of M.tb infection at 60 days post infection, suggests that IL-10 production by T cells and production of IL-27 by macrophages will further expand differentiation of Tr1 cells, which eventually leads to decreased ability of stressed old mice to control the infection." (PMID 36189368, 2022). "Additionally, IL-27 stimulation prior to infection led to significantly increased Mx1 transcription in our study, but it did not significantly increase Oas1-3 transcripts." (PMID 36678402, 2022). "Considering that IL-27 is highly upregulated in O. tsutsugamushi-infected mouse lungs and MΦ, we asked whether IL-27 may stimulate antiviral responses during infection." (PMID 36678402, 2022). "Alternatively, it is possible that IL-27/IL-27R signaling could extrinsically induce chemotaxis of innate immune cells to the infection site." (PMID 36028492, 2022). "In addition, IL-27 negatively regulates neutrophil recruitment at the site of infection and its downregulation has demonstrated to increase the levels of neutrophils." (PMID 35327327, 2022). "In our study, it is conceivable that the observed reduction in bone loss in rAAV-IL-27p28-treated mice was due to reduced infection and not due to the direct suppressive effects of IL-27 on osteoclast formation." (PMID 36028492, 2022). "To verify the relationship between IL-27 and liver injury in a CLP-induced severe infection mouse model, we first detected IL-27 levels in serum by ELISA and the expression levels of EBI3 and P28 (subunits of IL-27) in the liver tissue by q-PCR and Western blot." (PMID 33564275, 2021). "Together, both in vivo and in vitro data indicate that upon infection with Mtb, IL-27-mediated signalling may exert direct impact on different cell subsets of both the innate and adaptive immune response." (PMID 35116036, 2021). "IL-27 signaling is also important for the generation of IFNγ-producing CD8 T cells in infection." (PMID 34045653, 2021). "IL-27 is an important cytokine in the inflammatory response to liver injury after severe infection." (PMID 33564275, 2021). "Interestingly, several studies have indicated that macrophages and T cells primarily produce IL-27 in these infections." (PMID 34079555, 2021). "As IL-27 is mainly produced by macrophages and DCs, we speculate that macrophages may regulate liver damage by producing IL-27 in severe infections." (PMID 33564275, 2021). "As the previous studies reported that GdCl3 can inhibit the function of KCs, we speculated that the changes of the IL-27 level in the liver in the severe infection mouth model may be related to the inhibition of KCs." (PMID 33564275, 2021). "IL-27 is an antiviral cytokine that inhibits infection of HIV, HSV, and other viruses." (PMID 33525571, 2021).
infection (continued). "However, some cytokines, including interleukin-27, are expressed at multiple phases of the infection, such that their pro and anti-inflammatory functions have been difficult to interpret." (PMID 34079555, 2021). "Thus, our studies reveal that Tip-DCs mediate the early death of infected mice and that the development of Tip-DCs is negatively regulated by IL-27 signaling during infection." (PMID 33593983, 2021). "The reduction of liver injury by gadolinium chloride in severe infection mice models may relate to the inhibition of liver IL-27 production." (PMID 33564275, 2021). "In this report, Gr-1+ cells increased the production of IL-27 during an infection." (PMID 34208904, 2021). "Interestingly, IL-27 blockade accelerated mortality in the late infection phase with all mutant mice dying before day 300 of infection due to chronic hyperinflammatory responses." (PMID 34079555, 2021). "Therefore, the purpose of this review is to summarize the immunobiology of IL-27 in the context of bacterial infections and propose hypothetical mechanisms of IL-27-mediated immune homeostasis during these infections." (PMID 34079555, 2021). "We and others have recently shown that IL-27 downregulates CD4+ T cell activation and prevents fatal liver pathology during infection with African trypanosomes, protozoan parasites causing serious infections in humans and animals." (PMID 33593983, 2021). "In addition to CD4 and CD8 T cells, different target cells of IL-27 have been identified in other infection models." (PMID 34045653, 2021). "In a similar set of experiments, AMs obtained from control, D. pigrum 040417- and D. pigrum 030918-treated infant mice were challenged in vitro with S. pneumoniae serotype 3, and the levels of IFN-β, IFN-γ, IL-10, and IL-27 in culture supernatants were assessed 24 h post-infection." (PMID 34207076, 2021). "Therefore, IL-27 is dispensable for the development of immunity against L. donovani but delays the resolution of the parasite infection." (PMID 32849534, 2020). "The reduced IL-27 serum levels in C5ar1−/− animals during the acute stage of infection might explain the increased numbers of CD8+ and CD8−TH cells in the spleen of such mice as compared with wt animals." (PMID 32733463, 2020). "IL-27 can also influence infections that impact the peripheral nervous system (PNS)." (PMID 32802395, 2020). "High expression of TLR2 by DCs from BALB/c mice may support the early IL-27 expression after infection, which contributes to the attenuating of inflammation and promoting infection." (PMID 32849534, 2020). "IL-27 is a potent inhibitor of Th2 and Th17 cell development in helminth and protozoan infection, hence its downregulation may promote the amplified Th2 and Th17 responses observed in later CS infestation." (PMID 32886659, 2020). "Here we show that IL-27 signalling plays a pivotal role in generating Tr1 cells during infection, whereby Il27ra-/- mice had improved parasite control but accelerated splenic pathology, associated with an increased proportion of Th1 cells, relative to Tr1 cells." (PMID 33049000, 2020). "The gp130 cytokines IL-6, IL-11 and IL-27 differentially affect the outcome of infection with Mtb." (PMID 33334075, 2020). "IL-27 increased in circulation and peaked following the first day of infection in neonatal mice." (PMID 31818960, 2020). "Next, we tested if IL-27 expressing rAAV (AAV-IL-27) infection of B16 cells could lead to IL-27 production." (PMID 32292786, 2020). "The L. amazonensis-infected macrophages may be one of the main sources of IL-27 during the infection." (PMID 32849534, 2020). "IL-27 may represent a targeted adjunctive therapy to augment the efficacy of antibiotics to improve survival and infection-related outcomes in neonates." (PMID 31818960, 2020). "However, the mean fluorescent intensity of IL-27+ cells demonstrated that some cells elevated their level of cytokine production at different times during infection." (PMID 31818960, 2020).
infection (continued). "However, we cannot rule out other cellular sources that make a contribution to the overall levels of IL-27 produced during infection." (PMID 31818960, 2020). "• Splenic CD11chiMHCIIhi cDCs collected at days 21 and 28 post-infection express high IL-27 levels. • The DC-derived IL-27 may enhance the IFN-γ+ IL-10+ CD4+ cell polarization in vivo." (PMID 32849534, 2020). "It has also been reported that in NK cells, the expression of CD27 may determine the ability of cell migration, suggesting that IL-27 may promote the trafficking of a subset of NK cells to the infection site." (PMID 32722164, 2020). "IL-27 signaling is crucial in maintaining the subtle balance between Th1 and Th2 immunity, in which protective inflammation is upregulated within the early stages of infection and subsequently downregulated once microbial growth is controlled." (PMID 32802395, 2020). "Immunosuppressive cytokines such as IL-10 and IL-27 have been shown to be required in the chronic phase of infection to limit excessive inflammatory cytokine production and T cell proliferation, both of which can lead to fatal immunopathology in mice lacking IL-10 or IL-27 signaling." (PMID 31978191, 2020). "• The IL-27 administration into the infected footpads (on days 2, 4, and 6 after infection) enhances the lesion sizes and parasite number in the footpads and the draining lymph nodes in weeks 2 and 3 following infection." (PMID 32849534, 2020). "Therefore, the data shown here suggest that IL-27 regulates some immune genes to defend against diseases or pathogen infection." (PMID 31835347, 2019). "We may only speculate that the infection-induced expansion of the SV/129 Tfh cell compartment may be due to the same infection-induced IL-27 secretion observed in BALB/c mice." (PMID 30881923, 2019). "C3HeB/FeJ mice infected with MAC showed increased numbers of CD11b+ macrophages and CD11c+ dendritic cells expressing MHC class II during acute phase of the infection, however, this waned during the chronic phase of the disease when expression of IL-27 and PD-1L increased." (PMID 31001241, 2019). "In this infection group the frequency of IL-27 was reduced to 82%." (PMID 30619332, 2018). "In contrast to previous studies that focused on IL-27's ability to regulate T cells, we report here that IL-27R signaling largely influenced innate immunity and altered the inflammatory environment after infection, likely influencing long-term immunity." (PMID 29593047, 2018). "Having confirmed the cell type specific deletion of Il-27p28 in both genetic models, we next, analyzed KLRG1 and GrzA expression at different time points post infection to investigate which cellular source was important for IL-27 mediated regulation of a cytotoxic phenotype in antiviral CD4 T cells." (PMID 30044874, 2018). "Besides this immunogenic function, several studies have analyzed the regulatory function of IL-27 during infection with various different pathogens." (PMID 29541071, 2018). "In this study, we found that IL-27 expression was rapidly increased after LCMV Cl13 infection." (PMID 29593047, 2018). "Direct IL-27 signaling favors pDC accumulation early after LCMV Cl13 infection." (PMID 29593047, 2018). "Lower IL27 at 2 weeks seen in the hyperoxia group may permanently alter the flexibility in responding to infection, inflammation, and stress in adult mice." (PMID 29368801, 2018). "Loss of IL-27 signaling resulted in reduced IFN-I and dysregulated DC and NK cell numbers and/or activation, which correlated with a diminished capacity to control LCMV Cl13 early after infection." (PMID 29593047, 2018). "Importantly, however, during LCMV Cl13 infection, IL-27 limited the production of LCMV-specific IgG2a and IgG1, along with overall IgG avidity." (PMID 29593047, 2018). "We found that IL-27 enhanced the number of antiviral CD4 T cells upon infection." (PMID 30044874, 2018).